WNT2B (Wnt family member 2B)
Description:
Ligand for members of the frizzled family of seven transmembrane receptors. Functions in the canonical Wnt/beta-catenin signaling pathway. Plays a redundant role in embryonic lung development.
Synonyms: WNT13; XWNT2
Tractability: Antibody: UniProt places it where antibodies can reach, with high confidence; its Gene Ontology location is reachable by antibodies, with high confidence; UniProt predicts a signal peptide or a membrane-spanning region.
Gene: Protein-coding gene on chromosome 1 (112,466,541 to 112,530,165, forward strand). Ensembl gene ENSG00000134245.
Subcellular location: Secreted, extracellular space, extracellular matrix; Secreted
Subcellular location (Human Protein Atlas): Vesicles; Nucleoplasm; Predicted to be secreted
Pathways (Reactome):
Signal Transduction: Class B/2 (Secretin family receptors); WNT ligand biogenesis and trafficking
Gene Ontology:
Molecular function: protein binding; cytokine activity; frizzled binding; signaling receptor binding
Biological process: canonical Wnt signaling pathway; chondrocyte differentiation; forebrain regionalization; hematopoietic stem cell proliferation; male gonad development; cell fate commitment; cornea development in camera-type eye; iris morphogenesis; lens development in camera-type eye; neuron differentiation; animal organ development; system development; Wnt signaling pathway
Cellular component: extracellular matrix; extracellular region
Genetic constraint (gnomAD): Loss-of-function variants: 19 observed, 41.25 expected, observed/expected ratio (o/e) 0.46, 90% interval 0.32 to 0.68. The upper end of that interval is the gene's LOEUF score, 0.68, which puts it in group 2 of 6, group 1 being the genes least tolerant of losing a copy. Missense variants: 467 observed, 560.33 expected, observed/expected ratio (o/e) 0.83, 90% interval 0.77 to 0.9. Synonymous variants: 220 observed, 208.79 expected, observed/expected ratio (o/e) 1.05, 90% interval 0.94 to 1.18.
Homologues: Orthologues: chimpanzee WNT2B (100% identical), macaque WNT2B (98% identical), pig WNT2B (98% identical), rabbit WNT2B (98% identical), dog WNT2B (98% identical), guinea pig WNT2B (96% identical), rat Wnt2b (95% identical), mouse Wnt2b (95% identical), tropical clawed frog wnt2b (72% identical), zebrafish wnt2bb (71% identical), Drosophila melanogaster Wnt5 (41% identical), Caenorhabditis elegans cwn-2 (39% identical), and 4 more. Paralogues in human: WNT2 (62% identical), WNT5A (46% identical), WNT5B (46% identical), WNT7A (44% identical), WNT4 (43% identical), WNT7B (43% identical), WNT3 (40% identical), WNT10A (39% identical), WNT3A (39% identical), WNT16 (38% identical), WNT1 (38% identical), WNT10B (36% identical), and 6 more.
Diseases named in the same sentence as WNT2B in open-access papers:
WNT2B is named in the same sentence as 82 diseases in open-access papers, as found by Europe PMC text mining. Sharing a sentence is not in itself a finding about the gene and the disease. The quoted sentences say what the papers report.
nasopharyngeal carcinoma (10 papers, 2017 to 2022). A carcinoma arising from the nasopharyngeal epithelium. "Wnt2B is associated with clinical stage, T stage and cervical lymph node metastasis in patients with nasopharyngeal carcinoma." (PMID 33417298, 2021). "For example, miR-324-3p accelerates the development of gastric cancer through Smad4-mediated Wnt/β-catenin signaling,miR-324-3p restrains the invasion and migration in nasopharyngeal carcinoma via directly targeting WNT2B." (PMID 34980214, 2022). "Previous research indicated that miR-324-3p suppressed nasopharyngeal carcinoma cell migration and invasion through silencing WNT2B." (PMID 32565736, 2020). "miR-324-3p regulates cell growth and apoptosis by targeting Mothers Against DPP Homolog 7 (SMAD7), and inhibits the migration and invasion of nasopharyngeal carcinoma by targeting wingless-type MMTV integration site 2B (WNT2B)." (PMID 31694199, 2019). "This microRNA was also involved in the restraint of cancer cell growth and apoptosis by targeting SMAD7 and WNT2B, and predicted radiosensitivity of nasopharyngeal carcinoma." (PMID 28977865, 2017). "Moreover, miR-324-3p regulates WNT2B, one of the WNT ligands able to activate the WNT pathway and suppresses migration and invasion in nasopharyngeal carcinoma." (PMID 34547721, 2021).
cervical cancer (9 papers, 2013 to 2022). A primary or metastatic malignant neoplasm involving the cervix. "According to research, it was found that the transition of stromal fibroblasts into cancer-associated fibroblasts is mediated by Wnt2B, which is found to be enriched in exosomes secreted by cervical cancer cells." (PMID 36139618, 2022). "Exosomal Wnt2B protein from cervical cancer cells promoted the activation of fibroblasts, thereby facilitating the progression of cervical cancer." (PMID 35024437, 2022). "The exosomal transfer of cervical cancer Wnt2B activates Wnt/β-catenin signaling to activate fibroblasts into CAFs while survivin from breast cancer induces CAFs through SOD1 upregulation." (PMID 35052791, 2022). "Here, we show that high Wnt2B levels were positively correlated with the number of CAFs in cervical cancer (CC)." (PMID 33731705, 2021). "Wnt-2b is also found at high levels in serum exosomes from cervical cancer patients compared to healthy controls." (PMID 34202942, 2021). "Additionally, the miR-145 agomir was able to repress WNT2B expression, and further led to an inhibition of the Wnt/β-catenin signaling in cervical cancer cells." (PMID 32232409, 2020). "Wnt2b is also shown to be expressed in several types of human cancer, such as basal cell carcinoma, gastric cancer, breast cancer, head/neck squamous cell carcinoma, cervical cancer and leukemia." (PMID 24278135, 2013). "These Wnt2B signal transduction proteins interact with the fibroblast to mediate activation of the Wnt/β-catenin signaling pathway, diminishing the concentration of Wnt2B inhibiting these signal transduction pathways, and ultimately leading to a low concentration of CAFs in cervical cancer lesions." (PMID 36139618, 2022). "Interestingly, data from previous literature indicated that WNT2B promoted the development of multiple cancers, including NPC, cervical cancer, ovarian cancer, and so on, indicating that WNT2B acted as an oncogene and exerted opposite effects with microRNA-338-5p in regulating cancer progression." (PMID 34268117, 2021).
breast carcinoma (8 papers, 2013 to 2025). "In the previous study, we found by RNA sequencing analysis that various myxobacterial metabolites of KYC4048 are toxic to breast cancer cells involving WNT2B gene." (PMID 33746192, 2021). "Additionally, three candidate genes are associated with Breast cancer (DLL3, BRCA2, WNT2B), the mTOR signaling pathway (WNT2B, TELO2, TNFRSF1A), and Pathways in cancer (DLL3, BRCA2, WNT2B)." (PMID 40919429, 2025). "For instance, FOXF2 plays diverting roles on WNT2B and FZD1 promoters in lumenal breast cancer and BLBC." (PMID 40003882, 2025). "In luminal breast cancer cells, FOXF2 initiates the recruitment of NCoA3, forming a complex that attaches to the WNT2B and FZD1 promoters." (PMID 40003882, 2025). "Therefore, in luminal breast cancer and basal-like breast cancer cells, FOXF2 differentially modulates the transcription of WNT2B and FZD1 by enlisting NCoA3 and NCoR1, respectively." (PMID 40003882, 2025). "The results revealed that non-polar KYC4048 metabolites induced cell death of breast cancer cells and decreased expression levels of WNT2B, β-catenin, and Wnt target genes (c-Myc and cyclin D1)." (PMID 33746192, 2021).
hepatocellular carcinoma (7 papers, 2013 to 2024). A malignant tumor that arises from hepatocytes. "Hepatocellular carcinoma-educated macrophages’ promotion of epithelial-mesenchymal transformation via Wnt2b/β-catenin /c-Myc signaling and reprogramming glycolysis." (PMID 38773433, 2024). "Hepatocellular carcinoma-derived polarization-promoting factors promoted TAM polarization to the M2-like phenotype by activating the Wnt2b/β-catenin/c-Myc signalling pathway, which enhanced TAM glycolysis." (PMID 37491279, 2023). "The virus-induced secretion of WNT2B was also confirmed in cervical-derived HeLa and hepatoma Huh7 human cells." (PMID 23785285, 2013). "IL-10, transforming growth factor beta (TGF-β), and Wnt ligands from hepatocellular carcinoma (HCC) cells upregulate Wnt2b expression and promote M2 polarization in TAMs by activating the Wnt2b/β-catenin/c-Myc signaling axis and glycolysis." (PMID 39430253, 2024). "One study showed that TAMs are more prone to glycolytic metabolism in the hepatocellular carcinoma (HCC) tumor microenvironment, which depends on the activation of WNT2b/β-catenin/MYC signaling." (PMID 36966168, 2023). "Furthermore, WNT2B-conditioned medium was shown to induce the expression of EMT markers in hepatocellular carcinoma (HCC) cells, while medium of cells with knockdown of WNT2B conferred the opposite effect." (PMID 36982422, 2023).
ovarian carcinoma (5 papers, 2017 to 2023). A malignant neoplasm originating from the surface ovarian epithelium. "In ovarian cancer, Wnt2B inhibited tumour progression by downregulating the Wnt/β‐catenin pathway." (PMID 37859585, 2023). "miR-338-3p promotes apoptosis by downregulating WNT2B expression in ovarian cancer cells." (PMID 36564725, 2022). "In addition, WNT2B can increase the ability of metastasis and chemoresistance of ovarian cancer through the caspase-9/BCL2/BCL-xL pathway and EMT/p-AKT pathways." (PMID 28053597, 2017).
gastric cancer (4 papers, 2013 to 2024). A primary or metastatic malignant neoplasm involving the stomach. "The mRNA of WNT2B carries a binding site for microRNA- 376c-3p and that overexpression of microRNA-376c-3p reduces the expression of WNT2B, inhibiting the growth and promoting the apoptosis of gastric cancer cells." (PMID 38952556, 2024).
lung carcinoma (4 papers, 2018 to 2023). "More research is required to explore the lung cancer field where WNT2B is located, which may be a breakthrough point in subsequent studies." (PMID 35957916, 2022).
head and neck squamous cell carcinoma (3 papers, 2013 to 2020). A squamous cell carcinoma that arises from any of the following anatomic sites: lip and oral cavity, nasal cavity, paranasal sinuses, pharynx, larynx, and salivary glands. "In head and neck squamous cell carcinoma, WNT2B played a role in tumourigenesis and chemotherapy resistance in vivo and in vitro." (PMID 28053597, 2017).
Stroke (3 papers, 2021 to 2023). Sudden impairment of blood flow to a part of the brain due to occlusion or rupture of an artery to the brain. "Besides, a multiancestry GWAS meta-analysis identified a SNP in WNT2B (rs12037987) as the novel stroke risk loci." (PMID 34322525, 2021).
Alzheimer disease (2 papers, 2021 to 2023). A progressive, neurodegenerative disease characterized by loss of function and death of nerve cells in several areas of the brain leading to loss of cognitive function such as memory and language. "In the present study, we mainly found plasma Wnt2b levels in AD patients were decreased and positively correlated with cognitive function, and explored the pathological mechanism of Wnt2b in Alzheimer's disease in vitro and in vivo." (PMID 36852442, 2023). "This study investigated the relationship between plasma Wnt2b levels and Alzheimer's disease (AD), and explored the effect of Wnt2b on mitochondrial dysfunction in AD." (PMID 36852442, 2023).
coloboma (2 papers, 2016 to 2023). An abnormality in which a part of a structure in one or both eyes is missing. "In humans WNT2B mutations are associated with coloboma and WNT2B may also assist in retinal progenitor cell differentiation in chicken, yet the potential role of WNT2B in retinal neuronal development is understudied." (PMID 37048106, 2023).
colon cancer (2 papers, 2017 to 2020). "In contrast, the expression of other Wnts, including Wnt2b, 4, 7b, and 10b, does not change, as they remain strongly expressed in both normal colon and colon cancer." (PMID 28147310, 2017).
colorectal adenocarcinoma (2 papers, 2022). The most common type of colorectal carcinoma. "Moreover, expression of the majority of the genes (CACNA1H, COL1A1, COL11A1, FZD8, NGFR, SFRP2, WNT2B, and WNT5A) was associated with the ‘mesenchymal’ CMS group 4 in the TCGA (The Cancer Genome Atlas) Colorectal Adenocarcinoma dataset." (PMID 35892888, 2022).
Hypertension (2 papers, 2023 to 2025). The presence of chronic increased pressure in the systemic arterial system.
liver fibrosis (2 papers, 2017 to 2020). "Next, we evaluated whether the level of hepatic Wnt2b expression influenced the degree of liver fibrosis." (PMID 28638086, 2017). "Our data demonstrate that Wnt2b may serve as a novel endogenous suppressor of TLR4 signaling-mediated liver fibrosis." (PMID 28638086, 2017). "Consistently, in liver fibrosis mouse model established by repeated administration of thioacetamide (TAA), hepatic Wnt2b expression was also markedly increased compared to healthy controls, accompanied with highly expressed α-SMA." (PMID 28638086, 2017). "In addition, Wnt2b, serves as an endogenous inhibitor of TLR4 signaling, exhibited an inhibition on the HSCs activation and mitigated liver fibrosis." (PMID 32425800, 2020).
myopia (2 papers, 2014 to 2024). "Experiment I: investigate the potential trend of Wnt2b pathway in form-deprivation myopia (FDM) eyes induced by eyelid suture." (PMID 24755605, 2014). "Mice with form-deprivation myopia were found to show up-regulated wnt2b expression." (PMID 39607017, 2024). "Our studies provide the first evidence that the Wnt2b signaling pathway may play a role in the development and progression of form-deprivation myopia, in a mammalian model." (PMID 24755605, 2014). "The amounts of Wnt2b, Fzd5 and β-catenin mRNA and protein were significantly greater in form-deprived myopia eyes than in control eyes.DKK-1 (antagonist) reduced the myopic shift in refractive error and increase in axial elongation, whereas Norrin had the opposite effect in FDM eyes." (PMID 24755605, 2014). "Further investigation might target interactions between EFEMP1, WNT2B and EMT in myopia development." (PMID 39607017, 2024).
pancreatic cancer (2 papers, 2017 to 2021). "This is similar to previous findings that Wnt2B expression is significantly higher in human pancreatic cancer tissues than in normal pancreatic tissues, and patients with high Wnt2B expression have worse outcomes." (PMID 33417298, 2021).
prostate carcinoma (2 papers, 2022 to 2023). A carcinoma that arises from epithelial cells of the prostate gland. "Moreover, the lncRNA SNHG7/miR-324-3p/WNT2B regulatory axis was supposed as a new therapeutic target for prostate cancer." (PMID 38002073, 2023). "Wnt2B activation results in EMT induction in prostate cancer." (PMID 35773731, 2022). "LncRNA SNHG7, owing to its tumor-promoting role, can reduce miRNA-324-3p expression to elevate Wnt2B expression, resulting in EMT and progression of prostate cancer cells." (PMID 35773731, 2022).
viral infection (2 papers, 2013 to 2023). "Using brilliant databases and bioinformatics tools, we identified GABBR1-centered ceRNAs formed by PDGFRB and WNT2B via hsa-miR-19-3p and RNA-RNA interactions with HMGA1 and SMARCA4 as shared molecules between diabetes and viral infection." (PMID 37969011, 2023). "WNT2B and WNT9B secretion in response to viral infection induce a CTNNB1-dependent signaling pathway leading to decreased magnitude of IFNB1 production and effector response in a feedback inhibition mechanism." (PMID 23785285, 2013). "Here we show that secretion of WNT2B and WNT9B and stabilization of β-catenin (CTNNB1) upon virus infection negatively regulate expression of representative inducible genes IFNB1, IFIT1 and TNF in a CTNNB1-dependent effector mechanism." (PMID 23785285, 2013). "Overall, these results strongly support a specific effector role of virus-induced secretion of WNT2B and WNT9B ligands in innate immunity, acting in a feedback inhibition of IRF3- and NF-κB-dependent IFNB1 response to virus infection." (PMID 23785285, 2013). "Therefore, we concluded that we obtained a shared ceRNA network between diabetes and viral infections, which consisted of GABBR1, PDGFRB, WNT2B, and hsa-miR-19b/a-3p." (PMID 37969011, 2023).
acute myeloid leukemia (1 paper, 2025). Acute myeloid leukemia (AML) is a group of neoplasms arising from precursor cells committed to the myeloid cell-line differentiation. "WNT1 and WNT2b are expressed at high levels in acute myeloid leukemia (AML) blasts." (PMID 40805157, 2025).
adenoma (1 paper, 2025). A neoplasm arising from the epithelium. "In light of the preclinical findings identifying a role for stromal remodelling and wnt ligand dependency we assessed some very small human HMPS, TSA and conventional adenoma lesions to look for evidence of de-repressed CD55(+) Wnt2b(+) fibroblast cells." (PMID 40467544, 2025).
bipolar disorder (1 paper, 2021). A disorder of the brain that causes unusual shifts in mood, energy, activity levels and the ability to carry out day-to-day tasks. "However, it is interesting to note that expression of Wnt2b, upstream ligand of Wnt pathway also genetically associated with bipolar disorder, is significantly decreased in the ventral midbrain of A/J compared to C57BL/6J." (PMID 34503558, 2021).
bladder cancer (1 paper, 2022). "In all bladder cancer cases, Manhattan plot peaks satisfying p < 10−5 were observed near WNT2B in chromosome 1 and XYLB of chromosome 3, but they did not satisfy the suggestive association level of p < 10−4 in gene-wise analysis." (PMID 35328002, 2022).
cholangiocarcinoma (1 paper, 2020). A carcinoma that arises from the intrahepatic biliary tree (intrahepatic cholangiocarcinoma) or from the junction, or adjacent to the junction, of the right and left hepatic ducts (hilar cholangiocarcinoma). "A recent study has been reported that have reported miRNA-137 suppresses the proliferation, migration, and invasion of cholangiocarcinoma cells by targeting WNT2B." (PMID 33490245, 2020).
cleft palate (1 paper, 2022). Cleft palate is a fissure type embryopathy that affects the soft and hard palate to varying degrees. "Therefore, modulating Wnt2b expression may lead to cleft palate treatment caused by Foxf2 gene defects." (PMID 35668101, 2022).
colitis (1 paper, 2022). Inflammation of the colon. "For example, in acute phases of DSS-induced colitis, stromal cells secrete more Wnt2b, while infiltrating macrophages produce other Wnt ligands." (PMID 35190527, 2022).
endometrial carcinoma (1 paper, 2024). A malignant tumor arising from the epithelium that lines the cavity of the uterine body. "EFEMP1 has been previously shown to suppress the epithelial-mesenchymal transition in endometrial carcinoma through Wnt/β-catenin signaling, for which WNT2B is an activator." (PMID 39607017, 2024).
Familial exudative vitreoretinopathy (1 paper, 2023). Familial exudative vitreoretinopathy (FEVR) is a rare hereditary vitreoretinal disorder characterized by abnormal or incomplete vascularization of the peripheral retina leading to variable clinical manifestations ranging from no effects to minor anomalies, or even retinal detachment with blindness. "WNT2B binds Frizzled4 (Fzd4), and Fzd4 signaling is linked with familial exudative vitreoretinopathy in humans and in mice with incomplete development of retinal vasculature." (PMID 37048106, 2023).
glioblastoma (1 paper, 2022). The most malignant astrocytic tumor (WHO grade IV). "Additionally, miR-449b-5p was confirmed to inhibit the proliferation of glioblastoma by inactivating the WNT2B/Wnt/β-catenin signaling pathway." (PMID 35650603, 2022).